B2M (beta-2-microglobulin)
Diseases named in the same sentence as B2M in open-access papers (continued):
Sharing a sentence is not in itself a finding about the gene and the disease.
tumor (continued). "High HEV densities in B2M-mutant tumours underline the significance of immunoediting during tumour evolution." (PMID 31358939, 2019). "Since each individual’s tumor is unique, we quantified B2M and HLA mutations in terms of their allelic fraction percentile relative to other mutations observed in the same tumor." (PMID 31345234, 2019). "Of 61 tumours with wild‐type B2M, 18 (30%) had complete loss of B2M expression on IHC (specificity: 70%)." (PMID 31062389, 2019). "We found significantly higher HEV densities in tumours with a B2M mutation in comparison with B2M-wild-type MSI CRCs." (PMID 31358939, 2019). "Consistent with the known role of CD8+ CTLs in limiting cancer development, loss of these cells in mice that lack Cd8α or Beta-2-Microglobulin (a subunit of MHC I complex) both resulted in elevated tumor development in the large intestine." (PMID 31775909, 2019). "Though PTCH1 and B2M gene mutation correlates with the tumor growth, but it needs more proof to check the underlying mechanism between B2M mutation and the resistant response." (PMID 31692284, 2019). "In our study, B2M loss via epigenetic mechanisms did not confer complete protection from recurrence, as we identified three tumours with B2M protein loss in the presence of wild‐type B2M which recurred." (PMID 31062389, 2019). "The functionally-verified immune-resistance genes that were disproportionally mutated in hot tumours included those involved in antigen presentation (B2M and HLA-A), apoptosis (CASP8) and interferon signalling (JAK1)." (PMID 30104673, 2018). "In contrast to Pat99, loss of tumor-specific B2M protein expression was found in all samples from Pat25." (PMID 29070816, 2017). "Dysfunctional mutations in B2M have been viewed as an important mechanism of tumor resistance to T cell-mediated immune responses and lead to resistance to immunotherapy." (PMID 29299180, 2017). "As expected from the identified B2M frameshift mutations, a dramatic drop in tumor-specific B2M protein levels occurred after Pat208-developed resistance." (PMID 29070816, 2017). "Tissue staining showed loss of tumor-specific B2M protein expression during and after progressive disease, but not while the patient was responding." (PMID 29070816, 2017). "When comparing clinical and histopathological parameters, gene expression of HLA-A, HLA-B, B2M, and HLA-DR was positively associated with age at enucleation and with the largest basal diameter of the tumor, a well-known adverse parameter." (PMID 27764126, 2016). "In addition, disruption of the MHC I presentation mechanisms, as evidenced by mutations in β2‐microglobulin (B2M), contributes to acquired resistance by cloaking tumor cells from T cell surveillance." (PMID 40672434, 2025). "In addition, the tumor-immune correlation analysis demonstrated that PHF8 expression was strongly negatively associated with the levels of MHC class I genes including B2M, HLA-A/B/C, TAP1/2 as well as chemokines such as CCL5 and CXCL10." (PMID 40001243, 2025). "CD3 staining in both Yummer B2M KO and MC38 B2M KO mIL12 mRNA treated tumor sections, showed increased inflammatory responses in the periphery and a robust infiltration of T cells deep into the tumor and associated destruction of tumor cells." (PMID 40321762, 2025). "Prior investigations have revealed that B2M mutation may aid tumor cells to break away from the normal immune response and attenuate the efficacy of CTLs based immunotherapies by impeding MHC class I-mediated tumor antigen presentation." (PMID 40191187, 2025). "Notably, we have leveraged emerging technologies such as scRNA-seq, IMC, and CRISPR/Cas9 to deeply analyze the association between B2M and tumor immune therapy resistance." (PMID 40191187, 2025). "B2M is expressed by the other components of the tumor microenvironment, which could be causing T cell infiltration to the tumor." (PMID 41109214, 2025). "Up to 56% of cases with B2M or HLA-A loss were noted in the investigated tumor types." (PMID 38455061, 2024).
tumor (continued). "The extent of B2M loss varied considerably, depending on the tumor type and whether the sample was a primary tumor or distant metastasis." (PMID 38455061, 2024). "Furthermore, we provide more data that endorse the intensive investigation of B2M loss as a tumor escape mechanism in clinical trials using anti-cancer vaccines together with immune-checkpoint inhibitors." (PMID 38675779, 2024). "Genetic changes, such as homozygous or biallelic gene loss for B2M, lead not only to decreased HLA class I expression on tumour cells, but also increased resistance to immune checkpoint receptors targeting immunotherapy, e.g., anti-PD-1 and anti-CTLA-4 treatment." (PMID 36980527, 2023). "In addition, proteomics and immunohistochemical analysis revealed a significant downregulation of B2M in NK-NPC tumor cells, which was associated with EBV infection." (PMID 37098551, 2023). "The loss of functional B2M may be a mechanism of tumor resistance to T cell-mediated immune responses." (PMID 37465684, 2023). "Notably, cytotoxic CD8+ T lymphocytes kill tumor cells via the recognition and binding of tumor-associated antigens presented by the class I human leukocyte antigen (HLA-I) alpha chain and beta-2 microglobulin (β2 m)." (PMID 36838715, 2023). "Analysis of sorted MC38T/O tumor cells from Dox-treated mice showed elevated levels of Il6, β2-microglobulin (B2m), which associates with the MHC-I complex, and CD137-ligand (Cd137L), a ligand of the costimulatory receptor CD137, which is expressed on effector T lymphocytes." (PMID 37478172, 2023). "In this study, B2M-mutated subclones were selected early in tumour development." (PMID 36476325, 2022). "This study presented an OSCC cell line with innate mutations of HLA class I and depletion of B2M, which could be applied as an ideal model in tumor immune research." (PMID 36611830, 2022). "And this may be the reason why the B2M mutation may lead to a decrease in the total amount of MHC class I antigens presenting on the surface of tumor cells." (PMID 36046045, 2022). "The present consort prompts us to believe that B2M mutations in EBV positive DLBCLs might pave the way for the host immunotolerance to tumor cells through the deregulation of HLA expression and impairment of CD8+ T lymphocyte infiltration." (PMID 36606194, 2022). "This hypothesis implies that when B2M-defective tumor variants appear, these poorly immunogenic tumor clones become “invisible” to CTLs and thus acquire a growth advantage to take over the other clonal tumor populations." (PMID 36046045, 2022). "Although the Phase III trial of Allovectin-7 failed to meet key endpoints, the success of its Phase I/Phase II trials and related basic studies still demonstrates that B2M gene delivery can address the problems its mutation poses to T-cell-based tumor immunity." (PMID 36046045, 2022). "Studies have found that B2M is associated with antigen presentation in the tumour immune cycle." (PMID 34575074, 2021). "However, while loss of B2M as a mechanism of CPI resistance has been described in other tumor types, this has not been described to date in ccRCC." (PMID 34715028, 2021). "This important surveillance system termed ‘missing self’ results in NK-mediated destruction of circulating tumour cells and may account for the reduced incidence of disease recurrence in patients with mutations in B2M." (PMID 34302062, 2021). "In addition, GSVA analysis suggested that B2M suppressed the anti-tumor immune response associated with T cells." (PMID 33658560, 2021). "Moreover, immune evasion mediated by B2M loss was frequently observed in microsatellite instability (MSI) high tumors, and tumor with B2M loss was more resistant to immune checkpoint blockage (ICB) therapy." (PMID 33658560, 2021). "Interestingly these findings were confirmed in B2M low-expressing MMRd tumor patients, whereby the response to anti PD-1 was associated with high number of tumor infiltrated CD4+ T cells." (PMID 34072037, 2021).
tumor (continued). "AITL frequently has B2M mutations, which protect tumor cells from cytotoxic T-cell related damage." (PMID 34830782, 2021). "B2M mutations protect tumor cells against damage mediated by cytotoxic T cells." (PMID 34830782, 2021). "In addition, of the 7 nonresponders, 4 harbored two mutations of JAK1 (3 tumors) or B2M (1 tumor), possibly reflecting biallelic inactivation of these genes." (PMID 32494760, 2020). "They found that the LOH and upstream frameshift mutations in B2M were only extensively present during disease progression, suggesting immunoediting of B2M-mutated tumor subclones has already existed earlier in tumor development, or became dominant under selective pressure applied by ICBs." (PMID 32793604, 2020). "Three of 18 tumours with B2M protein loss in the presence of a wild‐type B2M gene recurred." (PMID 31062389, 2019). "Deleterious B2M mutations were detected in 39 of 121 (32%) dMMR tumours." (PMID 31062389, 2019). "B2M is one of the polypeptide chains of human leukocyte antigen class I (HLA class I), and both chains are essential for membrane expression of HLA class I. Loss of HLA class I expression provides an immune escape mechanism for tumor cells." (PMID 26752561, 2016). "This may reflect that antigen presentation, a process to which B2M is central, may need to be specifically altered according to the set of mutations already present in the tumor genome." (PMID 27043210, 2016). "Furthermore, MDR1, MRP, and LRP expression wasn’t associated with tumor stage, response to first-line therapy, the erythrocyte sedimentation rate, or C reactive protein, beta 2 microglobulin, serum lactate dehydrogenase, and albumin levels." (PMID 24744642, 2012). "These MSI-H tumours were further analysed for B2M mutation status." (PMID 22353804, 2012). "Interestingly, loss of the native HLA-A,B,C/B2M complex appears to be sporadic in nature; in some cases, the loss is localised to certain portions of the tumour, whereas in others, loss of B2M is evident across the entire tumour." (PMID 18506145, 2008). "To date, only one review has delved into the role of B2M in cancer immunotherapy, highlighting that B2M alterations are prevalent across various cancers and are linked to tumor immune escape and immunotherapy resistance, and may serve as a potential biomarker for ICIs treatment." (PMID 40191187, 2025). "Mutations in TNFRSF14 may lead to a tumor-supportive microenvironment through an increase in the production of cytokines recruiting T follicular helper cells, and mutations in B2M may lead to loss of expression of human leukocyte antigen class 1, which impairs CD8+ cytotoxic T-cell binding." (PMID 39392347, 2024). "In addition, we observed an increase in tumor B2m expression associated with CBD-IL-12 therapy." (PMID 37041154, 2023). "Similar to immunoediting, “evolutionary triage” eliminates mutations in tumor cells that increase susceptibility to the host immune response while mutations that shield them from immune attack increase proliferation and are readily observable (e.g., B2M mutations)." (PMID 36092893, 2022). "Although we could not confirm whether recognition by CTLs is enhanced by the upregulation of HLA-I and B2M, it has been well established that deficient expression of HLA-I components, including B2M, is a key factor contributing to tumor progression and immunotherapy resistance." (PMID 34458148, 2021). "Hemizygous loss of B2M, a component of major histocompatibility complex class I, was observed in all DFT1s except for the single ancestral divergent clade E tumour, presenting the possibility that this event, which likely confers lower immunogenicity, may have been favoured in early DFT1 evolution." (PMID 33232318, 2020).
tumor (continued). "We conclude that mutations to either component of MHC-I will provide effective escape in the setting of a robust anti-tumor immune response, however mutations to B2M may be more beneficial in settings such as MSI when the number of neoantigens generated is highest." (PMID 31345234, 2019). "Thus, we speculate that B2M mutations are likely to reduce the total amount of MHC-I molecules presenting antigens on the tumor cell surface, while HLA mutations would impact which mutations could be presented as neoantigens." (PMID 31345234, 2019). "By multiple comparisons of B2M protein expression associated with histopathological characteristics, we found that the positivity of B2M expression was not significantly different between various histological types in benign, borderline and malignant tumours (P > 0.05)." (PMID 26983758, 2016). "The two syngeneic B2M KO models utilized in this study demonstrated different tumor growth kinetics and baseline immune profiles." (PMID 40321762, 2025). "Looking ahead, several critical fields in B2M-related tumor immunotherapy research warrant further exploration." (PMID 40191187, 2025). "A clear loss of heterozygosity at the HLA locus was detected in the tumor of patient UC2, providing an explanation for the reduced intensity of the B2M staining." (PMID 41312368, 2025). "As the light chain of MHC-I molecule, B2M plays a pivotal role in tumor antigen presentation, with its expression modulated by diverse mechanisms such as genetics, epigenetics, cytokines, and non-coding RNAs." (PMID 40191187, 2025). "Markers such as creatinine, B2M, and albumin are also reflective of disease severity and tumor–host interactions." (PMID 41010591, 2025). "Subsequently, they established two patient-derived tumor organoid cell lines and generated B2M knockout (B2M KO) cell lines using CRISPR technology." (PMID 40191187, 2025). "In recent years, gene editing technologies (CRISPR/Cas9, TALEN, ZFN) have contributed to addressing GvHD and HvGA by knocking out TCR on allogeneic CAR-T along with MHC-I/B2M, thus improving the anti-tumor effectiveness of CAR-T cells." (PMID 40191187, 2025). "Monotherapy with mIL12 mRNA in the MC38 B2M KO tumor model, led to TGI effects in all animals in the group culminating in CRs in (7/10) and PRs in 3/10 animals." (PMID 40321762, 2025). "It has been found that radiotherapy can facilitate the release of interferon-beta (IFNβ) to upregulate B2M/MHC-I expression on resistant tumor cells, enhance antigen presentation, and restore responsiveness to PD-1 therapy." (PMID 40191187, 2025). "Combined results allowed to evaluate the efficacy of YT-Vav1+CISH–/– and YT–Vav1+B2M–/– modified NK cell lines at conditions close to tumor process development in the human body." (PMID 40071076, 2025). "The median initial and final beta-2 microglobulin values in the MF group with neoplasms were 2068 ng/mL (nanograms per milliliter) (range: 1259–3701) and 2339.5 ng/mL (range: 1448–6984), respectively." (PMID 40524021, 2025). "Immunohistochemistry showed that the small foci in the control tumors expressed both TSPY and B2M in the tumor cells." (PMID 40563082, 2025). "By participating in the antigen presentation process of MHC class I molecules, B2M influences T cell recognition and killing of infected or tumor cells." (PMID 41384115, 2025). "This review systematically elaborates on the role and reversal strategies of B2M in tumor immunotherapy resistance from multiple perspectives." (PMID 40191187, 2025). "Conversely, C2 tumor cells displayed a higher expression level of B2M, which is responsible for the stabilization of MHC class I molecules at the cell surface and is associated with immunotherapy sensitivity in clear cell RCC19." (PMID 39794332, 2025).
tumor (continued). "The final multi-omics model incorporated the following 10 initial genomic and transcriptomic biomarkers: response pathway, nsTMB, HED, fsIndel burden, defects in B2M, HLA-B27 supertype, tumor purity, TCR α chain entropy, IFNG-IMS ratio, and IGH entropy." (PMID 40075562, 2025). "IHC analysis with F4/80 antibody staining of the control treated B2M KO tumor sections from both models showed a dense and even distribution of TAMs throughout the tumor." (PMID 40321762, 2025). "MHC-I delivery of tumor antigens is mediated by the co-expression of several genes, including β2-microglobulin (B2M), a major component of MHC-I that presents antigens to CD8+ T lymphocytes." (PMID 40038799, 2025). "Evidently, it can be seen that in the context of B2M deficiency, the activation of CD4+ T cells and NK cells can also overcome resistance to exert anti-tumor functions." (PMID 40191187, 2025). "For instance, analysis of tumour biopsies revealed that B2M LOH is significantly more abundant in ICB‐resistant patients and correlates with unfavourable survival outcomes." (PMID 40673641, 2025). "Here, we observed a significant downregulation of B2M in metastases compared to primary tumor lesions of patients with SCLC." (PMID 41361170, 2025). "Loss‐of‐function mutations, gene deletions, or loss of heterozygosity (LOH) involving B2M impair MHC‐I presentation, rendering tumour cells invisible to CD8+ T lymphocytes." (PMID 40673641, 2025). "Multiplexed analysis of circulating factors in the serum derived from the mIL12 mRNA both Yummer 1.7 and MC38 B2M KO tumor bearing mice revealed elevated levels of cytokines responsible for major aspects necessary for successful antitumor responses." (PMID 40321762, 2025). "It was ascertained that the expression of HLA-I/B2M was positive after 72 hours, escalating the immunogenicity of tumor cells and the capability of T cell immune recognition." (PMID 40191187, 2025). "The reduction in B2M expression reflects a well-known mechanism of immune evasion, where tumor cells reduce their visibility to cytotoxic T cells, helping them evade immune detection." (PMID 40431665, 2025). "FCGR3A suggested active ADCC in NK cells, while high B2M expression enhanced tumor immunogenicity, helping suppress cancer." (PMID 40104502, 2025). "IFNγ can facilitate CD8+ T cell priming and infiltration by upregulating the expression of B2M/MHC-I on the surface of tumor cells." (PMID 40191187, 2025). "Elevated initial and final beta-2 microglobulin levels were observed in MF patients with neoplasms (p = 0.002 and 0.005, respectively)." (PMID 40524021, 2025). "Other enriched genes in blood- and tumor-TCR-matched populations included antigen presentation (β-2-microglobulin [B2M] and human leukocyte antigens [HLAs] for both MHC class I and class II)." (PMID 40299576, 2025). "The immune escape from T cells caused by the knockout of genes IFN-γ signaling pathway (JAK1, JAK2, Ifngr2) and antigen presentation pathway (TAP1, TAP2, B2M) promotes tumor vulnerability to NK cells." (PMID 40191187, 2025). "B2M is prevalently expressed in considerable nucleated cells, encompassing immune cells and tumor cells." (PMID 40191187, 2025). "Tumor fragment 5 stood out as the most “immune-hot” region, with elevated expression of B2M, HLA-I/II, TAP1/2, and markers of CD8/CD4 T cell infiltration, which in turn correlated with its high antigen abundances." (PMID 40777321, 2025). "Following 20 hours in co-culture, we observed significantly higher cancer cell killing when T cells were co-cultured with B2M transduced tumor cells (p = 0.035)." (PMID 41415427, 2025). "After 3 h of incubation with modified YT–Vav1+CISH–/– and YT–Vav1+B2M–/– NK cell lines, the spheroids lost their compact structure and tumor cells detached along the edge." (PMID 40071076, 2025). "B2M reflects tumor burden, renal function, and immune activation, while its elevation in kidney injury underscores its role as a renal marker." (PMID 41010591, 2025).